FLT3 (fms related receptor tyrosine kinase 3)
Diseases named in the same sentence as FLT3 in open-access papers (continued):
Sharing a sentence is not in itself a finding about the gene and the disease.
eosinophilia (13 papers, 2013 to 2026). "Cases of AML with JAK2 and FLT3 rearrangements are also included in the current WHO classification in the category of “myeloid/lymphoid neoplasms with eosinophilia and tyrosine kinase gene fusions”." (PMID 38337573, 2024). "Myeloid (and lymphoid) neoplasms with eosinophilia are associated with rearrangement of the tyrosine kinase (TK) genes, namely PDGFRB, PDGFRA, FGFR1, JAK2, FLT3, and ABL1 (excluding BCR-ABL1)." (PMID 39156600, 2024). "Several other gene rearrangements involving JAK2 (located on chromosome 9p24) and FLT3 (located on chromosome 13q12) may rarely manifest as AML with clonal eosinophilia." (PMID 38337573, 2024). "This category name has changed from the previous “myeloid/lymphoid neoplasms with eosinophilia and rearrangement of PDGFRA, PDGFRB or FGFR1, or with PCM1::JAK2” (MLN-eo), to specify the underlying molecular genetic changes and to include cases with ETV6::ABL1, FLT3 fusions or other TK fusion genes." (PMID 37454239, 2023). "Myeloid or lymphoid neoplasms with eosinophilia can demonstrate gene rearrangements in PDGFRA, PDGFRB, FGFR1, JAK2, or FLT3 or ETV6::ABL or other tyrosine kinase gene fusion (MLN-TK)." (PMID 38611061, 2024). "In the case of eosinophilia, FISH/cytogenetics and molecular analysis (on bone marrow aspirate or peripheral blood cells) should specifically look for PDGFRA, PDGFRB, FGFR1, FLT3, ETV6, and JAK2 gene rearrangements." (PMID 37274287, 2023). "Eosinophilia is present in almost all cases of MLN-TK, caused by fusion genes involving a receptor [PDGFRA or B, fibroblast growth factor receptor (FGFR), fms like tyrosine kinase 3 (FLT3)], a transcription factor (ETV-6), or a non-receptor kinase (Janus kinase 2, JAK2)." (PMID 37274287, 2023). "Nearly 100 different TK fusion genes, involving at least six TK (PDGFRA, PDGFRB, FGFR1, JAK2, ABL1, FLT3), have been identified in distinct MLN with or without eosinophilia." (PMID 39037514, 2024). "To date, more than 70 different TK fusion genes with recurrent involvement of at least six TK (PDGFRA, PDGFRB, FGFR1, JAK2, ABL1, FLT3) have been identified in clinically and morphologically distinct MLN with or without eosinophilia." (PMID 37454239, 2023).
myelofibrosis (13 papers, 2012 to 2024). A partial or complete replacement of the bone marrow stroma by fibrous tissue. "On February 28, 2022, the FDA granted accelerated approval to Pacritinib, a highly effective inhibitor of JAK2 and FMS-like tyrosine kinase 3 (FLT3), which was used to treat adult patients with low platelets who suffer from intermediate or high-risk primary or secondary myelofibrosis (MF)." (PMID 37661221, 2023). "Fedratinib is a JAK2/FMS-like tyrosine kinase 3 (FLT3) inhibitor that received FDA approval for the treatment of myelofibrosis." (PMID 35056105, 2021). "Pacritinib is a novel “multi-target” agent, developed for myelofibrosis, which inhibits JAK2/FLT3/IL-1 receptor associated kinase (IRAK1)/colony stimulating factor 1 receptor (CFS1R)." (PMID 35056105, 2021). "Fedratinib, an oral, potent JAK2 inhibitor effective against wild-type and mutationally activated JAK2 and fms-like tyrosine kinase 3 (FLT3), was approved in 2019 for treatment of adult patients with intermediate-2 or high-risk primary or secondary myelofibrosis." (PMID 33322351, 2020). "Because of the inhibition of FLT3, it is studied clinically in myelofibrosis and AML." (PMID 22532837, 2012). "Pacritinib, an inhibitor of both wild-type and mutant (V617F) JAK2 as well as FMS-like tyrosine kinase 3 (FLT3), is employed in the treatment of primary and secondary myelofibrosis (MF) in adult patients with significantly weakened platelet counts." (PMID 37513921, 2023). "Fedratinib, an oral selective JAK2 inhibitor targeting FMS-like tyrosine kinase-3 (FLT-3), was approved by the Food and Drug Administration (FDA) in 2019 for the treatment of primary or secondary myelofibrosis, eight years after the introduction of ruxolitinib." (PMID 38999955, 2024).
anemia (11 papers, 2012 to 2025). A reduction in the number of red blood cells, the amount of hemoglobin, and/or the volume of packed red blood cells. "Herein we described the development of anemia in patients carrying FLT3 gene mutation." (PMID 24744665, 2012). "In the phase 3 trials of both the JAK1/JAK2 inhibitor ruxolitinib and JAK2/FLT3 inhibitor fedratinib, indicators of anemia worsening such as decreased mean hemoglobin levels and increased transfusions were evident in the initial weeks of treatment." (PMID 39682250, 2024). "One possible explanation was that blockade of FLT-3 and Kit by TKIs leads to anemia-induced hematopoietic insufficiency." (PMID 37377925, 2023). "Anemia (Hb 8–10 g/dl), platelets <50.000/μl, FLT3-ITD, and subtype of AML (primary vs. secondary) were the variables with a significant influence on survival in our model." (PMID 29963245, 2018). "These mice displayed disease manifestations of shortened survival, myeloid expansion in the bone marrow (exaggerated in cases of LOH of wild type Flt3), anemia, erythroid dysplasia, and a relatively decreased M:E ratio compared to the Flt3+/ITD mice." (PMID 30450160, 2018). "In multivariate analysis anemia, platelets, FLT3-ITD, and therapy-related disease remained in the model." (PMID 29963245, 2018). "The thrombocytopenia and anemia associated with fedratinib may be related to its on-target inhibition of WT JAK2 and off-target inhibition of FMS-like tyrosine kinase 3 (FLT3) and bromodomain-containing protein 4 (BRD4)." (PMID 35903543, 2022).
colorectal cancer (11 papers, 2013 to 2025). A primary or metastatic malignant neoplasm that affects the colon or rectum. "Previous studies have demonstrated that FLT3 is detectable at the mRNA and protein levels in colorectal cancer tissues, despite the rarity of FLT3 mutations in CRC." (PMID 40427072, 2025). "Based on this, we hypothesized that FLT3 amplification might be a potential therapeutic target in colorectal cancer and investigated further using FLT3-amplified PDC from colorectal cancer patients." (PMID 27906677, 2017). "As a highly potent and highly selective oral inhibitor of FLT3/AXL, gilteritinib showed activity against FLT3D835 and FLT3‐ITD mutations in pre‐clinical testing, although its role on colorectal cancer (CRC) cells is not yet fully elucidated." (PMID 31881122, 2020). "Linifanib is an inhibitor of FMS-like tyrosine kinase 3 (FLT3) and vascular endothelial growth factor receptor (VEGF) tyrosine kinases, and is involved in clinical trials concerning non-small cell lung cancer (NSCLC), breast, liver, and colorectal cancer as well as leukemia." (PMID 32523056, 2020). "However, based on our data, FLT3 may not be an “actionable” target, at least in colorectal cancer, either as monotherapy or combined therapy." (PMID 27906677, 2017).
Thrombocytopenia (11 papers, 2017 to 2025). A reduction in the number of circulating thrombocytes. "We speculate that FLT3 738 C-allele carriers tend to be more susceptible to early-onset thrombocytopenia and require dose reduction." (PMID 28335742, 2017). "Blood disorders, including neutropenia and thrombocytopenia, can be induced by SU through binding to Fms-like tyrosine kinase 3 (FLT-3) expressed on the surface of hematopoietic cells." (PMID 36980737, 2023). "Our data indicate that at least a subpopulation of lung Mks were much longer lived than are BM Mks, originated via a Flt3-negative pathway from HSCs, and increased platelet production in response to thrombocytopenia." (PMID 39302653, 2024).
glioma (10 papers, 2012 to 2025). A benign or malignant brain and spinal cord tumor that arises from glial cells (astrocytes, oligodendrocytes, ependymal cells). "FLT3 (receptor-type tyrosine-protein kinase) mutations were related to poor prognosis in gliomas." (PMID 36676646, 2022). "The identification of other oncogenic ITDs in pediatric cancer (e.g. FLT3 ITD in AML13 and FGFR1 ITD14 in low-grade glioma) has typically relied on PCR-based assays." (PMID 40348911, 2025). "It turned out to be a selective FLT3, KIT, and PDGFR-β inhibitor and increased the apoptotic glioma-cell numbers and arrested sub-G1-phase cell cycle." (PMID 33218150, 2020). "On the contrary, 43 driver genes were down-regulated expression and related to favorable clinical outcomes in glioma patients, such as PIK3R1, FLT3, PIK3R1 and RUNX1T1." (PMID 29046615, 2017). "In females, strong discordance for VEGFR, PDGFR, and FLT3 blockade, coupled with suppression of mitotic-segregation pathways, argues for combining anti-angiogenic or RTK inhibitors with HDAC inhibitors and neuron-glioma coupling modulators (e.g., clinically tractable NMDAR antagonists)." (PMID 41514565, 2025). "For example, using Flt3–Cre lineage tracing, microglia-derived TAMs composed about 65% of the bulk TAM population in glioma, while using CX3CR1GFP/WT; CCR2RFP/WT knock-in mice, over 85% of the TAMs within the glioma are thought to be derived from inflammatory monocytes." (PMID 33919979, 2021).
myeloid sarcoma (10 papers, 2016 to 2026). A tumor mass composed of myeloblasts or immature myeloid cells. "The most common genetic mutation found to be associated with myeloid sarcomas in general is the FLT3-TKD mutation, being found in around 17.5% of patients." (PMID 41438662, 2026). "Given the emerging significance of FLT3 mutations in myeloid sarcomas, comprehensive testing for all FLT3 variants is crucial to determine the appropriate treatment modality." (PMID 38738062, 2024). "Further analysis of the sequencing results revealed missense mutations in the FLT3 and PTPRB genes, which are associated with myeloid sarcoma." (PMID 36871023, 2023). "In another patient with myeloid sarcoma and history of treatment-related AML, this included an ASXL1 indel and FLT3 ITD." (PMID 39687881, 2024). "One patient with NRAS, MPL positivity, FLT3/NPM1 WT had received 2 courses of high-dose cytarabine inductions with residual BM blast burden 80% and dural myeloid sarcoma." (PMID 35039473, 2022). "Some case reports found FLT3-ITD and NPM1 variations in myeloid sarcomas with high frequencies of 15 and 14.4 %, respectively." (PMID 27724883, 2016).
neutropenia (10 papers, 2015 to 2025). A decrease in the number of neutrophils found in the blood. "Univariate Cox regression showed that classical risk factors such as age, type of AML, FLT3 status, type of chemotherapy, duration of neutropenia, disease status after treatment, HSCT, and diagnosis of IFIs have a significant impact on survival." (PMID 40647482, 2025). "It is noteworthy that the FLT3 738 TT genotype was associated with an 8.0-fold increase in the risk of leucopenia (P = 0.03) and a 2.7-fold increase in the risk of neutropenia (P = 0.04)." (PMID 26244574, 2015). "There is a strong association of the FLT3 738T genotype with leucopenia; FLT3 738T, ABCB1 1236T, ABCB1 3435T, ABCB1 2677T, ABCG2 421A alleles and the ABCB1-3435-1236-2677 TTT haplotype with neutropenia; and primary resistance and inferior survival with the ABCB1-3435-1236-2677 TTT haplotype." (PMID 34948113, 2021). "We observed significant associations of FLT3 738T (OR=2.7), ABCB1 1236T (OR=0.3), ABCB1 3435T (OR=0.1), ABCB1 2677T (OR=0.4), ABCG2 421A (OR=0.3) alleles and ABCB1 3435, 1236, 2677 TTT haplotype (OR=0.1) on neutropenia." (PMID 26244574, 2015). "Both FLT3 and KIT kinases play an important role in hematopoiesis and their inhibition may result in neutropenia as observed in the clinical trials for barasertib." (PMID 33915740, 2021).
non-small cell lung carcinoma (10 papers, 2012 to 2025). A group of at least three distinct histological types of lung cancer, including non-small cell squamous cell carcinoma, adenocarcinoma, and large cell carcinoma. "Oral administration of JNJ-28312141, an FMS-related receptor tyrosine kinase-3 (FLT3) inhibitor, caused dose-dependent suppression of human non-small cell lung carcinoma growth and reduced tumor vasculature in nude mice, which correlated with marked reductions in F4/80+ TAMs." (PMID 28660349, 2018). "In immune checkpoint blockade (ICB)-resistant non-small cell lung cancer (NSCLC), PU.1 and Flt3 expression are reduced, leading to inhibited differentiation of classical Ly6C+ monocytes into DCs/TAMs." (PMID 40612857, 2025). "Tyrosine kinase inhibition has proved to be a promising strategy to support cancer therapy against non-small cell lung carcinoma (EGFR inhibitors) and leukemic malignancies (CML: ABL inhibitors; AML: FLT3 inhibitors; ALL: ABL inhibitors)." (PMID 31614680, 2019). "Clinical effectiveness of another mitotic-poisoning agent, docetaxel, was also improved in non-small-cell lung carcinoma (NSCLC) patients when used in combination with nintedanib, a non-selective inhibitor targeting all subtypes of VEGFRs, FGFRs, and PDGFRα and β, together with RET and FLT3." (PMID 41154409, 2025).
gastric cancer (9 papers, 2015 to 2025). A primary or metastatic malignant neoplasm involving the stomach. "In this study, the incidence of FLT3 amplification is 1.6% (20 patients) and the majority was gastrointestinal tumors (colorectal and gastric cancers)." (PMID 27906677, 2017). "Among 50 gastric cancer tissues, FLT3 gene amplification (3.7-fold) was noted only in one sample." (PMID 27906677, 2017). "Hotspot mutations occurring in the codon 835 of the FLT3 oncogene have been implicated in the majority of AML and ALL patients, and recurrent aberrations such as D816V and V560D found in the KIT oncogene have been associated with patients suffering from AML and gastric cancer, respectively." (PMID 34068918, 2021). "Treatment with each inhibitor in breast and gastric cancer cells had negligible effects on TAZ expression, suggesting that the FLT3-JAK-STAT3-TAZ-TEAD signaling is unique to FLT3+ CML cells." (PMID 37932786, 2023).
lung adenocarcinoma (9 papers, 2020 to 2026). A carcinoma that arises from the lung and is characterized by the presence of malignant glandular epithelial cells. "We previously reported that CPZ inhibits the proliferation of AML and lung adenocarcinoma cells harboring activating RTK mutations by disrupting CCV formation and altering the subcellular localization of RTKs such as FLT3-ITD and c-Kit V617F." (PMID 41150745, 2025). "In our study, we show that FLT3 expression is a favorable prognostic factor in patients with lung squamous cell carcinoma and lung adenocarcinoma." (PMID 38327131, 2024). "On the other hand, PEBP1, FLT3 and IL33 were adversely associated with the outcomes of lung adenocarcinoma patients." (PMID 39311766, 2024). "Genetic alterations of FMS-Like Tyrosine Kinase 3 (FLT3) characterize about 25–30% of AML cases as well as several solid tumors such as lung adenocarcinoma and gastrointestinal cancer." (PMID 37803464, 2023). "Moreover, FLT3 is a potential targeted protein and has been reported as an immune-related prognostic gene in lung adenocarcinoma, indicating the clinical value of FLT3." (PMID 36146599, 2022). "Here we show the relationship between FLT3 gene expression and disease‐free survival in patients with lung squamous cell carcinoma (LUSC) and lung adenocarcinoma (LUAD) and immune cell infiltration with particular emphasis on the role of NK and stimulatory DC cells subpopulations." (PMID 38327131, 2024).
prostate carcinoma (9 papers, 2007 to 2022). A carcinoma that arises from epithelial cells of the prostate gland. "Our finding that Pim inhibition abrogates induction of C-NHEJ activity by topoisomerase 2 inhibitor treatment in cells with FLT3-WT is consistent with this finding in prostate cancer and peripheral T-cell lymphoma cells." (PMID 34504649, 2021).
atherosclerosis (8 papers, 2013 to 2025). A disease characterized by the build-up of fatty material and calcium deposition in the arterial wall resulting in partial or complete occlusion of the arterial lumen. "In atherosclerosis, cDC1 increase in the aorta and ablation of cDC1 by deleting Flt3, a cytokine receptor, leading to increase of atherosclerotic lesion size and plaque area, concomitantly with decrease of Treg cells." (PMID 35693801, 2022). "This implies protective roles of cDC1 in the pathogenesis of atherosclerosis, although it should be kept in mind that Flt3 deletion results in decrease of cDC2 as well as cDC1." (PMID 35693801, 2022). "Consequently, FLT3 has been proposed to be a drug target for autoimmunity and inflammation, particularly atherosclerosis." (PMID 25531068, 2014). "Also, recent reports show a protective effect of Flt3 signaling dependent DCs against atherosclerosis." (PMID 23349985, 2013).
B-cell acute lymphoblastic leukemia (8 papers, 2011 to 2024). A neoplasm of lymphoblasts committed to the B-cell lineage, typically composed of small to medium-sized blast cells. "Previously, we have demonstrated that dexamethasone-resistant B-cell acute lymphoblastic leukemia cells that express the oncogenic mutant of FLT3 display upregulation of AXL expression upon inhibition of FLT3." (PMID 36835239, 2023). "Our data is therefore consistent with the observation that FLT3 inhibitors have therapeutic effects in B cell acute lymphoblastic leukemia with high level of FLT3 expression." (PMID 21552520, 2011). "We identified over 1000 tyrosine phosphorylation sites from about 750 proteins in both AML (wild type and mutant FLT3) and B cell acute lymphoblastic leukemia (normal and amplification of FLT3) cell lines." (PMID 21552520, 2011). "Limited studies have investigated the implications of the FLT3 gene in B-cell Acute Lymphoblastic Leukemia (B-ALL), likely due to the infrequent occurrence of FLT3 alterations." (PMID 39711880, 2024).